MMP9 (matrix metallopeptidase 9)
Diseases named in the same sentence as MMP9 in open-access papers (continued):
Sharing a sentence is not in itself a finding about the gene and the disease.
colon carcinoma (continued). "Therefore, MMP-2, in addition to MMP-9, represents a potential target molecule for treating malignant colon tumors." (PMID 34885656, 2021). "Moreover, the expression of active caspase‐3, p21 and E‐cadherin was up‐regulated and the expression of cyclin D1, c‐Myc, vimentin, N‐cadherin and MMP9 was down‐regulated in OCA‐treated colon cancer cells." (PMID 33164339, 2020). "In this study, the blockage of CA-induced cell invasion was observed in SW620 cells with pretreatment of MMP-9 antibody, DPI, or NAC, indicating that ROS production by NADPH oxidase plays an important role in CA-induced MMP-9 expression as well as colon cancer cell invasion." (PMID 32408577, 2020). "In the present study, we observed that CA treatment could increase colon cancer cell invasiveness and elucidated the molecular mechanisms of CA-induced MMP-9 expression." (PMID 32408577, 2020). "A more specific activity inhibition targeted exclusively to MMP-9, particularly in colon cancer, where this MMPI might act in situ, may be of significant potential to anticancer and anti-inflammatory approaches in the gastrointestinal diseases." (PMID 33308217, 2020). "Previous studies have shown that a number of dried fruit body Hericium erinaceus extractions could reduce the expression of MMP-2 and MMP-9 in human colon cancer and invasion through modulations of the phosphorylation of ERK, JNK, and p38 MAPK." (PMID 31680958, 2019). "In addition, Rg3 inhibits the migration of colon cancer cells by suppressing the expression of nuclear factor-κB- (NF-κB-) regulated gene products, including MMP-9." (PMID 30915362, 2019). "Moreover, Curcumin can inhibit colon cancer cell invasion by suppressing NF-κB-mediated transcriptional activation MMP9." (PMID 30473630, 2018). "Another key molecular mediator of DC-SIGNR in colon cancer cells is MMP9." (PMID 28109307, 2017). "Thus, we concluded that DC-SIGNR, as an important regulator, promoted colon cancer cell migration, invasion and metastasis through the activation of metallothioneins by upregulating MMP9 expression." (PMID 28109307, 2017). "However, in the current study, we injected doxycycline intraperitoneally after the development of adenoma in animal model of colon carcinoma and analysed its invasive activity by observation of augmented MMP-9 levels." (PMID 26998758, 2016). "Furthermore, it has been shown that AEG-1 knockdown inhibits invasion and decreases the MMP-9 expression in colon cancer cell lines." (PMID 27835571, 2016). "In colon cancer, the increased expression and activity of Src tyrosine kinase has been associated with persistent activation of the p130Cas/JNK pathways, the induction of MMP-2 and MMP-9, and invasion/survival in an α1-integrin-dependent fashion." (PMID 26356564, 2015). "Furthermore, high levels of MMP-9 expression in colon cancer cells correlated with lymph node metastasis and with Dukes’ stage." (PMID 24476461, 2014). "One hint might be the observed cleavage of Laminin5, since this process is in most part mediated by MMP-1 and MMP-7, and only in little part by MMP-9, in colon cancer." (PMID 24913355, 2014). "In addition, our results show that miR-34a directly down-regulated MMP9 that seems different from other studies, in which miR-34a indirectly down-regulates MMP9 expression through suppression of Fra-1 in colon cancer and DLL1 in choriocarcinoma." (PMID 25268950, 2014). "However, the correlation between MMP-9 expression and survival or prognosis in colon cancer is still inconclusive." (PMID 24476461, 2014). "Detected by using a luciferase reporter construct and western blots, piwi-like protein 2 (Piwil2) may regulate a 2-kb MMP-9 promoter fragment and apoptotic pathways in colon cancer." (PMID 24476461, 2014). "Here, our results showed that MMP-9 might be correlated with the metastasis of lymph node, and its elevated expression might be an adverse prognostic indicator for the patients of colon cancer." (PMID 24476461, 2014).
colon carcinoma (continued). "The MMP-9 expression that could be detected by immunohistochemistry may be a useful molecular marker to predict the prognosis in colon cancer patients." (PMID 24476461, 2014). "In conclusion, our study suggests that MMP-9 plays an important role in invasion and metastasis of colon cancer, and thus becomes a useful indicator for clinical assessment of tumor biological behavior and prognosis in colon cancer patients." (PMID 24476461, 2014). "The miRs -211, 491-5p and 885-5p target and inhibit gelatinase B/MMP-9 expression and are down regulated in human glioblastoma multiforme, in association with increased gelatinase B/MMP-9 expression, and miR-19a has been reported to regulate gelatinase B/MMP-9 expression in colon cancer cells." (PMID 24473089, 2014). "However, MMP-9, which degrades the basement collagen membrane, has been reported to be a particularly important proteolytic enzyme involved in colon cancer cell invasion." (PMID 24765211, 2014). "In this study, we found that MMP-9 expression in colon cancer tissues (47/68, 69.1%) was significantly higher than that in corresponding distal normal mucosa tissues (3/68, 4.4%), and there was a statistically significant difference (χ2 =64.602, P <0.001) between them." (PMID 24476461, 2014). "Meanwhile, IL-6 and MMP9 have been shown to promote the growth of colon cancer." (PMID 24397824, 2014). "MMP-9 is correlated with the metastasis of lymph nodes, and its elevated expression may be an adverse prognostic indicator for the patients of colon cancer." (PMID 24476461, 2014). "UA also suppressed colon cancer cell migration by inhibiting MMP9 and upregulating CDH1 expression." (PMID 23737956, 2013). "Moreover, gelatin zymography and ELISA analysis showed that MMP-9 activity and plasmin activity of colon cancer HCT116 cells were inhibited by ulinastatin, respectively." (PMID 23710449, 2013). "The results showed the anti-proliferation, anti-migration and pro-apoptotic effects of UA in colon cancer cells were mediated through simultaneous modulation of multiple signaling pathways, including MMP9/CDH1, Akt/ERK, COX-2/PGE2, p300/NF-κB/CREB2 and cytochrome c/caspase-dependent pathways." (PMID 23737956, 2013). "Both mRNA levels MMP-2 and MMP-9 have been found to be overexpressed in colon carcinomas." (PMID 21859479, 2011). "In the literature, re-introduction of TFAP2α into TFAP2α-negative SW480 colon cancer cells stimulates expression of E-cadherin and down regulation of the MMP-9 expression and leads to dramatic loss of cellular invasive potential in vitro." (PMID 21489314, 2011). "The role of such proteases may instead be the cleavage of HSPG core protein to enable diffusion of HS-bound VEGF, which was shown for MMP9 in a HT29 colon carcinoma spheroid model." (PMID 20686621, 2010). "Furthermore, we have reported that αvβ6 induces its own expression in an autocrine manner with cell crowding and proposed a self-perpetuating model of colon cancer progression regulated through αvβ6-mediated MMP-9 secretion." (PMID 12177807, 2002). "Heterologous expression of αvβ6 in a colon cancer cell line that lacks constitutive αvβ6 expression has been shown by us to enhance tumour growth in vitro and in vivo thought to be due, in part, to αvβ6-mediated matrix metalloproteinase-9 (MMP-9) secretion." (PMID 12177807, 2002). "To investigate whether the effects of fruquintinib on the migration and invasion of colon cancer cells are associated with EMT, we detected the expression of N-cadherin, E-cadherin, MMP-9 and vimentin following treatment with different concentrations of fruquintinib." (PMID 40134588, 2025). "In addition, systemic MMP9 levels were also shown to be increased in colon tumor bearing mice." (PMID 39664453, 2024). "Therefore, it was reasonable to speculate that MMP‐9 may also be of particular importance for H3NT proteolysis reactions in colon cancer cells." (PMID 38600695, 2024).
colon carcinoma (continued). "Moreover, we found that the activity of MMP9 analyzed using zymography was slightly decreased in TMEM211-silenced cells compared to those in scramble cells, suggesting that TMEM211 might regulate MMP2 and MMP9 for metastasis in colon cancer." (PMID 37367036, 2023). "Furthermore, the protein levels of PCNA protein (a marker for cell proliferation), cyclin D1 and cyclin E (key regulators of the cell cycle), and MMP-9 (a key regulator of metastasis in colon cancer), as well as TNFα (a marker for extrinsic cell apoptosis) in nude mice were measured by IHC." (PMID 36979011, 2023). "Also, the expression of MMP9 is connected with the prognosis of colon cancer." (PMID 36147444, 2022). "Interestingly, CDK8 stimulates expression of MMP-9 in human colon cancer cells via Wnt/β-catenin-driven transcription, while MED12 plays an important role in regulating and mediating the function of CDK8 kinase module, and the activation of CDK8 kinase also requires the participation of MED12." (PMID 35456498, 2022). "From this point of view, the incorporation and maintenance of the nutraceutical activities of lupin in baked cookies could be used to produce functional foods for the prevention and amelioration of chronic diseases related to MMP-9, such as inflammatory bowel diseases and colon cancer." (PMID 34441706, 2021). "Additionally, our previous research demonstrated that integrin αvβ6 could increase the expression and secretion of MMP-9 in colon cancer and cholangiocarcinoma, which also plays a role in migration of these two cancers." (PMID 32328185, 2020). "Therefore, we expect that CLSE may have anti-metastatic effects via regulation of E-cadherin, vimentin, MMP-2, and MMP-9 in colon cancer cells, and plan to undertake these experiments in the future." (PMID 29110726, 2017). "In the case of colon cancer or inflammatory bowel diseases, a more convenient and effective approach could be achieved, at least partly, through the long-term ingestion of natural food-born specific MMP-9 inhibitors that may be colon-available." (PMID 28264435, 2017). "Furthermore, we explored the relationship between MMP9 and metallothioneins in colon cancer cells." (PMID 28109307, 2017). "The results of this study could provide new evidence for the research of MMP-9 in colon cancer." (PMID 24476461, 2014). "In addition, a recent study revealed a similar result in the cell-free supernatant obtained from probiotic L. caser and L. rhamnosus GG that may decrease MMP-9 activity and inhibit colon cancer invasion." (PMID 24765211, 2014). "Next, our results indicate that MB-653 inhibits the invasivity of colon cancer cells by decreasing Snail (Caco2 and HCT116) and MMP-9 (Caco2)." (PMID 39858466, 2025). "In our previous study, C. militaris grown on germinated soybeans suppressed mRNA expression levels of MMP-9 and MMP-3 in colon cancer tissues." (PMID 39940873, 2025). "In colon cancer cells, miR-22 transfection has been reported to significantly reduce the expression of MMP-2 and MMP-9." (PMID 41583211, 2025). "Another key question arising from these xenograft growth data is to what extent MMP‐9 knockdown and inhibition affect H3NT proteolysis in SW620 colon cancer xenograft models." (PMID 38600695, 2024). "This reduction in MMP9 expression is achieved through the inhibition of PI3K and AKT, thereby decreasing the invasive potential of colon cancer cells." (PMID 39664453, 2024). "This inhibition is linked to the ability of intestinal stents to suppress the activity of inflammation-related cells, possibly including those responsible for producing MMP-9 and COX-2 in colon tumors." (PMID 38535948, 2024). "Of special relevance to the current report, previous studies demonstrated that MMP‐9‐induced ECM remodeling and membrane protein cleavage play an important role in the development, invasion, and metastasis of colon cancer." (PMID 38600695, 2024).
colon carcinoma (continued). "In a recent report, it was shown that MMP-9 is overexpressed and responsible for catalyzing H3NT proteolysis in colon cancer cells." (PMID 39409117, 2024). "These shared mechanisms of colon cancer and CIPN pathophysiology suggest MMP9’s potential contribution to neuropathic conditions in CRC patients, positioning it as a critical factor in disease progression and a promising therapeutic target." (PMID 39664453, 2024). "Very recent research showed that PLE0 also suppressed the expression and enzymatic activity of MMP-2 and MMP-9, while simultaneously increasing the protein and mRNA levels of TIMP-1 in HT-29 and HCT 116 human colon cancer cells." (PMID 39858430, 2024). "As another approach to examine the relationship between MMP‐9 and H3NT proteolysis in colon cancer cells, we repeated western blotting with colonic tumor and adjacent normal tissue samples from 10 patients." (PMID 38600695, 2024). "In checking MMP‐9 expression levels in four stages of colon cancer, MMP‐9 overexpression was detected in the four stages of colon cancer with only minor variations." (PMID 38600695, 2024). "Before we started, we detected the expression levels of MMP3, MMP9, TIMP1, VEGFA in various colon cancer cell lines by qRT-PCR assay, and found that these genes were highly expressed in RKO and SW480, and we chose RKO and SW480 for the following experiments." (PMID 39177661, 2024). "An important question remaining to be answered is about the initial recruitment mechanism of MMP‐9 to target genes for its H3NT proteolytic and transactivation functions in colon cancer cells." (PMID 38600695, 2024). "In this report, we demonstrate that MMP‐9 is overexpressed and responsible for catalyzing H3NT proteolysis in colon cancer cells." (PMID 38600695, 2024). "Since MMP‐9 inhibitor MMP9‐I is effective in blocking MMP‐9 protease activity, we also evaluated its effects on H3NT proteolysis in colon cancer cells as an extension of the knockdown studies." (PMID 38600695, 2024). "All these results strongly imply that MMP‐9 is the protease capable of recognizing H3 and catalyzing H3NT clipping in colon cancer cells." (PMID 38600695, 2024). "Auraptene has been reported to suppress matrix metalloproteinase (MMP)-2, MMP-7, and MMP-9 expression in human colon cancer cells, as well as MMP-2 and MMP-9 activity, to inhibit the migration and invasion of cancer cells." (PMID 37447286, 2023). "The activation of AMPK induced by EGCG in HT-29 colon cancer cells also exhibited interaction with VEGF and matrix metalloproteinase-9 (MMP-9)." (PMID 36677797, 2023). "Prominent MMPs, such as gelatinase A (MMP-2) and gelatinase B (MMP-9), are essential for the proteolytic cascade-driven breakdown of the ECM during colon cancer spread." (PMID 37037467, 2023). "Matrix metallopeptidase-9 (MMP-9) degrades extracellular matrix proteins and was increased in colon cancer patients." (PMID 35463337, 2022). "Both sevoflurane and desflurane can have pre-treatment on neutrophils to inhibit the release of matrix metalloproteinase-9 (MMP-9) and then restrain the metastasis of colon cancer cells." (PMID 35966857, 2022). "The secreted factors from L. casei and L. rhamnosus GG (LGG) downregulated matrix metalloproteinase-9 (MMP-9) and increased the level of tight junction protein ZO-1 in colon cancer." (PMID 36428575, 2022). "PEITC inhibited the invasion and migration of human colon cancer HT29 cells by decreasing SOS-1, PKC, ERK1/2, and Rho A which led to the reduction of MMP-2 and MMP-9." (PMID 35368876, 2022). "A previous study revealed that ethanol mediated both the activation of Nrf2 and HO-1 to maintain colon cancer cell survival through matrix metallopeptidase 2 (MMP2), MMP9 and VEGF, thus leading to a more aggressive phenotype." (PMID 35417854, 2022). "A densitometric quantification of Pro-MMP9 and Pro-MMP2 in all analyzed samples confirmed statistical differences between colon cancer tissues and paired normal tissues." (PMID 34830271, 2021).
colon carcinoma (continued). "The majority of the colon cancer tissues showed lytic activities corresponding to the latent and activated forms of MMP2 and MMP9." (PMID 34830271, 2021). "The levels of MMPs including MMP-2, MMP-9, MMP-11, and MMP-19 are elevated in the colon cancer patients as compared to normal individuals." (PMID 34096454, 2021). "Isoalvaxanthone, a natural xanthone derivative isolated from plants, also had similar activities in SW620 colon cancer cells, additionally inhibiting Rac1 factor and subsequently reducing the expression and activity of MMP-2 and MMP-9." (PMID 34680113, 2021). "In colon cancer, p38 gamma MAPK overexpression was leading to enhanced c-Jun synthesis, which in turn triggers the amplification of the transcription of MMP-9 and MMP-9 dependent invasion." (PMID 34096454, 2021). "Knockdown of BC200 blocks the invasion of HCT-116 and HT29 colon cancer cells via downregulation of MMP-2 and MMP-9." (PMID 33246471, 2020). "This activity is possible because colon cancer cells produce matrix metalloproteinase 2 (MMP-2) and matrix metalloproteinase 9 (MMP-9), gelatinases which dissolve type IV collagen, the essential component of BM." (PMID 32403316, 2020). "Both MMP9 and MMP12 proteins were increased in colon cancer epithelial cells compared to controls, with MMP12 proteins having more than 2-fold increase, while MMP9 proteins had a 1.3-fold increase in cancer cells compared to normal cells." (PMID 32171282, 2020). "It is worth noting that integrin αvβ6mediates the potential for colon cancer cells HT29 to colonize in and metastasize to the liver Its over–expression promotes MMP–9 secretion, enhances migration on fibronectin, and the survival of cancer cells in the liver." (PMID 32033352, 2020). "The EMT was significantly enhanced in FABP4-overexpressed colon cancer cells, as evidenced by the upregulation of Snail, MMP-2 and MMP-9, and the downregulation of E-cadherin." (PMID 33088219, 2020). "In previously published results, we have shown that MMP-9 is upregulated in peripheral blood NK cells of colon cancer patients and the TIMP-1/MMP-9 axis, as well as uPAR, are altered, as compared to normal circulating NK cells." (PMID 33569050, 2020). "Phosphorylation levels of these three proteins of MAPK pathways were all increased in a time-dependent manner, suggesting that the CA-induced MMP-9 expression was mediated through MAPK (ERK1/2, JNK, p38 MAPK) activation in human SW620 colon cancer cells." (PMID 32408577, 2020). "A study on HT-29 colon cancer cells showed that exposure to DCA in concentrations ranging from 20 μM to 80 μM resulted in an increased expression and activation of MMP-9 in a concentration-dependent manner." (PMID 33126685, 2020). "In conclusion, our results demonstrate that CA can induce MMP-9 expression through ROS-dependent ERK1/2, JNK-activated AP-1, and p38-MAPK-activated NF-κB, thus promoting the invasion of human colon cancer cells." (PMID 32408577, 2020). "To check this, we transfected pre-miR-21 in colon cancer LS174 cells and found a similar increase in MMP-2, MMP-9 and MMP-11, as was seen when cells were exposed to cancer cell-derived exosomes." (PMID 32427870, 2020). "Western blots were used to survey the inhibitory ability of Lactobacillus CFS on the protein levels of MMP2, MMP9, and VEGFA in colon cancer cells." (PMID 33228670, 2020). "In our study, the EMT phenotype markers changed significantly in FABP4-overexpressed colon cancer cells: the upregulation of Snail, MMP-2 and MMP-9, as well as the downregulation of E-cadherin." (PMID 33088219, 2020). "We further verified the effective compounds, by analysing the key genes MMP2, MMP9, and VEGFA in the VEGF-MMPs signalling pathway of colon cancer cells using real-time (RT)-PCR." (PMID 33228670, 2020).